KRTAP9-1 (keratin associated protein 9-1)
Description:
In the hair cortex, hair keratin intermediate filaments are embedded in an interfilamentous matrix, consisting of hair keratin-associated proteins (KRTAP), which are essential for the formation of a rigid and resistant hair shaft through their extensive disulfide bond cross-linking with abundant cysteine residues of hair keratins. The matrix proteins include the high-sulfur and high-glycine-tyrosine keratins (By similarity).
Synonyms: KAP9.1; KRTAP9L3
Tractability: No criterion of Open Targets' tractability assessment is met for any kind of drug.
Gene: Protein-coding gene on chromosome 17 (41,189,887 to 41,190,639, forward strand). Ensembl gene ENSG00000240542.
Pathways (Reactome):
Developmental Biology: Keratinization
Gene Ontology:
Cellular component: cytosol
Genetic constraint (gnomAD): Loss-of-function variants: 13 observed, 17.66 expected, observed/expected ratio (o/e) 0.74, 90% interval 0.48 to 1.17. The upper end of that interval is the gene's LOEUF score, 1.17, which puts it in group 5 of 6, group 1 being the genes least tolerant of losing a copy. Missense variants: 306 observed, 303.81 expected, observed/expected ratio (o/e) 1.01, 90% interval 0.92 to 1.11. Synonymous variants: 120 observed, 106.23 expected, observed/expected ratio (o/e) 1.13, 90% interval 0.97 to 1.32.
Homologues: Orthologues: chimpanzee KRTAP9-1 (98% identical), mouse Krtap9-5 (46% identical), rat LOC120098854 (31% identical), rat Krtap10-9 (31% identical), mouse Krtap10-32 (30% identical), mouse Krtap10-21 (30% identical), mouse Krtap10-25 (30% identical), mouse Krtap10-29 (30% identical), mouse Krtap10-33 (30% identical), mouse Krtap10-22 (30% identical), mouse Krtap10-26 (30% identical), mouse Krtap10-31 (30% identical), and 21 more. Paralogues in human: KRTAP9-2 (56% identical), KRTAP9-7 (54% identical), KRTAP9-9 (54% identical), KRTAP9-6 (51% identical), KRTAP9-8 (51% identical), KRTAP9-3 (50% identical), KRTAP9-4 (49% identical), KRTAP4-12 (36% identical), KRTAP4-6 (35% identical), KRTAP4-9 (34% identical), KRTAP4-11 (34% identical), KRTAP4-4 (33% identical), and 35 more.